CD4 (CD4 molecule)
Diseases named in the same sentence as CD4 in open-access papers (continued):
Sharing a sentence is not in itself a finding about the gene and the disease.
tumor (continued). "In 2009 Banissi and coworkers reported that low-dose metronomic TMZ regimens (0.5 and 2 mg/kg for 21 days) induced a significant decrease in Foxp3+Treg/CD4+ ratios in the spleen of tumor-bearing animals." (PMID 23725550, 2013). "The levels of CRP have been inversely related to tumor-infiltrating CD4+ T-lymphocytes within the tumor microenvironment, which in turn carriers a poor prognosis." (PMID 23409924, 2013). "Collectively, these data suggest that CD4+ T cells can gain cytotoxic activity against tumor cells when CD8+ T cells are not active but this activity is tightly controlled by Tregs during tumor rejection." (PMID 22890822, 2013). "A higher infiltration of CD3+CD4+ cells relative to CD3+CD8+ cells was found both at the tumor front and in its core." (PMID 23634283, 2013). "CD4 T cells play a critical role in mediating adaptive immunity to a variety of pathogens as well as in tumor immunity." (PMID 23874332, 2013). "Further, we reported that CD4+ T cells expressing CD39 or CD73 were present in tumor tissues (HNSCC), and that at least some CD4+CD25+ Treg infiltrating these tumors co-expressed the two markers in situ." (PMID 23898333, 2013). "Presentation of tumour H-Y antigens to CD4+ and CD8+ T cells can be measured using H-Y-specific T cells from transgenic mice expressing a single TCR recognizing I-Ab-Dby [Marilyn mice], or Db-Uty [MataHari mice], respectively." (PMID 24142880, 2013). "In contrast to the robust proliferation of Tim-3− counterparts, tumor-derived Tim-3+CD4 T cells were anergic to anti-CD3/CD28 stimulation, characteristics shared by “classical” human Treg cells." (PMID 23526963, 2013). "For example, the presence of CD4+ Tregs appears to influence the anti-tumor activity of tumor-infiltrating cytotoxic CD8+ T cells." (PMID 23382860, 2013). "Because CD4+ cells are essential for activation of CTL response, it is noteworthy that calcarea carbonica, in the present study, normalized CD4+ cells in different immune organs of tumor-bearing host." (PMID 24053127, 2013). "Tumor-specific CD4+ T cells seem to be less important for tumor rejection when functional CD8+ T cells are present." (PMID 22890822, 2013). "There we were successful in attaining objective anti-tumor responses that correlated with surrogate markers such as CD4+ and CD8+ T cell responses and humoral responses." (PMID 23870437, 2013). "Our data are in agreement with those which show that CD4+ T cells are also involved in anti–tumor effector activity through a perforin-mediated mechanism." (PMID 23981284, 2013). "Even in patients with tumours showing cPRs, the AbN CD4+ CD25+ Tregs were still 4 fold elevated, compared with HFDs (p = 0.008)." (PMID 23320561, 2013). "All iNKT cell clones tested in cytotoxic assays were CD4+ or DN and showed similar capacity of tumor-targeted cell killing." (PMID 23242316, 2013). "Our studies show that when CD8+ T cells were unable to control FBL-3 tumor development, cytotoxic effector CD4+ T cells were able to take over and eliminate the tumor." (PMID 22890822, 2013). "We showed the distribution of BM-derived inflammatory cells (CD11c+, Ly-6C and CD4+ T cells) in the tumor microenvironment." (PMID 24040017, 2013). "On day 39, purified CD4+ splenic T cells from animals with similar tumor burden were tested for reactivity to CEA protein in an in vitro lymphoproliferation assay." (PMID 23894654, 2013). "In another study, the same group reported the establishment of CD4+ Treg clones generated from tumor-infiltrating lymphocytes of cancer patients which were reactive against another tumor-derived ARTC1 peptide." (PMID 23874336, 2013). "In our study, preferential homing of Th1 CD4 T cells to intracranially implanted tumours correlated with high expression of CXCR3, which is a receptor for IFN-γ-inducible protein (IP)-10/CXCL10." (PMID 23717511, 2013).
tumor (continued). "Despite the anti-tumour potential of CD4 T cells, they are currently underexploited because of uncertainties about generating cells in vitro with the capacity to home to the tumour site and exert appropriate in vivo functions." (PMID 23717511, 2013). "Tumor-derived CD4 T cells were sorted into Tim-3+ and Tim-3− subsets, and then cocultured with responder cells on anti-CD3/CD28 stimulation for 5 days." (PMID 23526963, 2013). "CD4+ regulatory T cells have been identified that are specific for a variety of tumor antigens, including antigens commonly targeted by vaccination such as gp100, NY-ESO-1, HER2/neu, and CEA." (PMID 23653893, 2013). "The differentiation of naïve T cells into mature CD8 Teff or CD4 Th1 or Th17 cells is required for T cells to make full use of their functional attributes directed against tumor cells, such as cytotoxicity and production of IFNγ and TNFα." (PMID 24265631, 2013). "In a human melanoma study, for example, CD4+Foxp3+ Treg cells infiltrating tumor tissue not only displayed upregulated expression of ICOS but also exhibited a more potent suppressive activity compared to those derived from circulating blood cells." (PMID 23874336, 2013). "Bone marrow-derived inflammatory cells in the tumor microenvironment promote tumor angiogenesis, tumor proliferation, survival and invasion and suppress the specific anti-tumor immune response of CD4 and CD8 lymphocytes." (PMID 24040017, 2013). "CCR5 deficiency (demonstrated by use of CCR5−/− mice) or CCL5 blockade (using Met-RANTES) led to diminished CD4+Foxp3+ T cells numbers and slower tumor growth." (PMID 23874342, 2013). "Taken together, these data demonstrate that anti-CTLA-4 and chemotherapy synergize in the induction of a potent anti-tumor immune response, with an important role for both CD4+ and CD8+ T cells for optimal therapeutic effect." (PMID 23626745, 2013). "Existing cancer vaccination approaches have employed either tumour expressed CD4 epitopes, or “universal” CD4 epitopes, in an attempt to provide overall T cell help." (PMID 23717511, 2013). "Their results supported the central role played by CD4+ T cells not only in providing help for optimal priming and expansion of anti-tumor CD8+ T cells, but also as active effectors of the immune response." (PMID 23981284, 2013). "The in vivo depletion of CD4+ T cells one day before tumor challenge resulted in compromised vaccine efficacy in both TC-1 (25%) and 3LL (12.5%) tumor models." (PMID 24066030, 2013). "In any instance, the most characterized CD4 Th cell subset is the Th1 that can potentially produce large amounts of IFN-γ upon tumor antigen encounter and expresses the transcription factor T-bet." (PMID 23533029, 2013). "Th1 cells, of which IFN-γ+ secreting CD4+ cells are a prototypic example, are known to play a role in anti-tumor immunity." (PMID 23667456, 2013). "Suppression by cognate-antigen-specific iTreg cells was restricted to CD4+ T cells and occurred only within the local tumor environment while suppression of CD8+ T-cell response was independent of these tumor-antigen-specific iTreg cells." (PMID 23874336, 2013). "It has especially been shown Tregs prevent CD8+T cell maturation by inhibiting CD4+T cells in tumor sites." (PMID 24078089, 2013). "In adoptive transfer experiments, purified CD4+CD25− T cells transferred into tumor bearing mice have been shown to convert into Foxp3+CD4+CD25+ cells within the tumor microenvironment." (PMID 23874342, 2013). "In contrast, over 60% of tumor-infiltrating Tim-3+ CD4 T cells expressed CD25, and ∼80% of Tim-3+ CD4 TILs were CD127low, two characteristics shared by human Treg cells." (PMID 23526963, 2013). "The administration of both anti-mouse CD4 and anti-mouse CD8 neutralizing antibodies abrogated the anti-tumor effect of the combined treatment (p = 0.034, anti-CD4 versus control; p = 0.0245, anti-CD8 versus control)." (PMID 23935988, 2013).
tumor (continued). "In contrast, CD8+ T lymphocytes, type 1 CD4+ T lymphocytes, NK, type 1 natural killer T cells, M1 macrophages, and immune killer dendritic cells promote tumor destruction." (PMID 24833054, 2013). "Transfer of CD4 T helper cells was reported to enhance CD8 T cell numbers at the tumour site in other tumour models." (PMID 23717511, 2013). "Such roles are mediated, in part, by the production of signature cytokines by specific CD4 T cell lineages and through direct cytotoxic effects on tumor cells." (PMID 23533029, 2013). "Infiltration with CD8+ T cells is necessary for complete tumor eradication and CD4+ T cells help in achieving adaptive immune response." (PMID 23360213, 2013). "Reports have shown that activation of tumor-specific CD4+ helper T (Th) cells is crucial for effective anti-tumor immunity and identification of Th-cell epitopes is critical for peptide vaccine-based cancer immunotherapy." (PMID 24386437, 2013). "Toward this end, mice that had eradicated primary tumors in response to vaccination one day post-CD4+ T cell depletion were given a second dose of tumor cells 60 days post primary tumor challenge." (PMID 24066030, 2013). "These cells are induced in the periphery or at tissue/tumor sites from the naïve CD4+CD25(−) T cells in the presence of IL-10 or TGF-β and exert suppression by the production of soluble suppressor factors." (PMID 23898333, 2013). "The presence of FoxP3+CD4+CD25+ T regulatory cells (Tregs) possibly with immunosuppressive activity was evaluated in tumor tissues, inflammatory tissue and draining lymph nodes (LNs) in 198 PDAC patients and 15 patients with non-neoplastic lesions." (PMID 23950747, 2013). "It has been shown that, similar to CD8+ cells, CD4+ cells harboring human MHC class I- restricted specific TCRs exhibit anti-tumor activity in vivo and in vitro and are suggested to be as efficacious as CD8+ T cells." (PMID 23437112, 2013). "Paying particular attention to the micro-anatomic location in tumor tissues, here we observed that the majority of Tim-3+CD4+ cells in the peritumoral stroma were Foxp3−, whereas the majority of Tim-3+CD4+ cells in the cancer nest co-expressed Foxp3." (PMID 23526963, 2013). "Among the tumor-infiltrating cells analyzed, CD4+ T cells were statistically increased in WEHI-164 and K7M2 tumor-bearing mice which had been subjected to all protocol treatments, in comparison with untreated tumor–bearing mice." (PMID 24156020, 2013). "Differentiation of naïve CD4+ T cells into iTreg cells in the periphery is encouraged by tumor antigen in the presence of certain cytokines such as IL-2, IL-10, and TGF-β." (PMID 23378947, 2013). "Our results show that RFA induces a plethora of immune events based on dose, including immunogenic modulation of tumor and CD4+ and CD8+ T-cell responses." (PMID 23894654, 2013). "There is a similar requirement for the processing of parenchymal self antigen by host DC in the induction of CD4+T cell tolerance in tumor." (PMID 24040017, 2013). "Taken together, these data indicate that tumor-derived VEGF is required to attract CD4+Foxp3+Nrp1+ T cells that can support tumor growth." (PMID 24324469, 2013). "We observed significant numbers of CD8+/CD4+ T cells that secreted IFN-γ in the presence of mHER-2-positive tumors as well as CD4+ T cell infiltration at the tumor site." (PMID 23870437, 2013). "Pulaski and colleagues have shown that IL-3 enhances tumor rejection via development of cytotoxic effectors by a mechanism that requires CD4+ cells, and they demonstrated that IL-3 induced the antigen cross presentation ability of macrophages." (PMID 23441198, 2013). "By extrapolation, it is assumed that CD4+ T cells also play a similar role in immune responses against tumors, which was substantiated by using autologous tumor-specific CD4+ T cells for adaptive immune therapy against cancer." (PMID 24066030, 2013).
tumor (continued). "Supporting this notion, CD4+ or CD8+ circulatory effector T cell populations were also severely decreased in peripheral blood of the tumor-bearing mice." (PMID 24053127, 2013). "In recent years, the idea that CD4+ T cells can also play a considerable role in protective anti-tumor responses has received growing attention." (PMID 22890822, 2013). "In tumor-bearing mice there was an obviously high proportion of CD4+ T and CD8+ T cells after exposure to MF." (PMID 24278103, 2013). "A smaller but significant increase in CD4+ Tcm cells was achieved only in double dosed animals from 2.83% to 6.25% (p = 0.0487) on day 22 post-tumor implant." (PMID 24829750, 2013). "Human CD4+CD25neg T cells and autologous immature dendritic cells (iDC) were co-incubated with irradiated tumor cells and a cytokine mix containing IL-2, IL-10, and IL-15 (20 IU/mL of each) for 10 days at 37 °C." (PMID 23898333, 2013). "Peak expansion of specific CD4+ T cells was found as early as at 6 days post-tumor challenge, whereas CD8+ T-cell expansion reached its maximum 2 days later." (PMID 22890822, 2013). "The percentage of tumor-infiltrating Foxp3+CD4+ T cells was significantly decreased in tumors treated with gemcitabine, anti-CTLA-4 or the combination treatment, a finding consistent with previously published data." (PMID 23626745, 2013). "Our analyses of T cell cytokine expression and the overall local cytokine milieu suggested that co-transfer of Th1 CD4 T cells with CD8 T cells would have a significant anti-tumour effect." (PMID 23717511, 2013). "Tumor-specific Tregs actively suppress the proliferation of CD4+CD25− and CD8+ effector T cells, thereby limiting the immune response against cancer and contributing to tumor growth." (PMID 23589107, 2013). "Control experiments showed that this anti-tumor effect was exclusively mediated by effector CD4+ T cells." (PMID 22890822, 2013). "CD4+CD25+Foxp3+ cells were significantly reduced in the total splenocytes as well as tumor tissues from HS-1793 (resveratrol analog)-administered mice, and the production of TGF-β inducing Treg showed a similar pattern." (PMID 24073240, 2013). "In this study, we found the combination therapy decreased the frequency of Tregs, and increased CD8+ T cells and CD4+ T cells at tumor sites, with increased levels of IL-12 and IFN-γ and decreased IL-10 and TGF-β1." (PMID 24304581, 2013). "The analysis on the T-cell tumor infiltrates showed an increase of CD4+granzyme+ T-cells and a decreased number of CD4+CD25+Foxp3+ Treg elements from mice treated with either gp10025-33 peptide-pulsed DC vaccination or anti-IL-10 mAb administration." (PMID 23663506, 2013). "We next sought to evaluate the impact of anti-CTLA-4 and GVAX combination immunotherapy on tumor antigen-specific CD4 T cell numbers and function." (PMID 23557194, 2013). "In this regard, it is known that the prevalence of CD4+CD25high T cells in tumor draining lymph nodes and the spleens of mice bearing the pancreatic adenocarcinoma Pan02, increases with tumor growth." (PMID 23378947, 2013). "The EOC-specific recruitment of CD4+CD25+FoxP3+ regulatory T-cells (Treg), tolerogenic dendritic cells (DC), B7-H4+ tumor-associated macrophages (TAM) and myeloid-derived suppressor cells (MDSC) fosters immune privilege and predicts reduced survival in EOC." (PMID 23763830, 2013). "To this aim first we implemented a culture method previously set for detection of the presence and quality of spontaneous viral and tumor Ag-specific CD4+ T cells in the blood of healthy individuals and neoplastic patients." (PMID 22879946, 2012). "In contrast, CCR4, a chemokine receptor associated with Th2 and Treg responses, was reciprocally expressed, i.e. there was a higher frequency of CCR4+ cells in CD4+ conventional T cells and Treg in the tumor than in the unaffected mucosa." (PMID 22319577, 2012).
tumor (continued). "Increased CD4+ICOSHi T cells have been reported to infiltrate tumor tissues and are found in peripheral blood after ipilimumab." (PMID 22788688, 2012). "Her2/neu over-expression was significantly (p < 0.001) associated with increased numbers of tumor infiltrating FOXP3+ T cells and by a similar trend for CD4+ lymphocytes (p = 0.023)." (PMID 22471961, 2012). "Tumor infiltrating CD4+ cells play a central role in immune protection through their production of cytokines and chemokines, thus orchestrating immune responses." (PMID 23275325, 2012). "Tumor-specific CD4+ T cells overcome this obstacle by collaborating with macrophages and dendritic cells." (PMID 22649466, 2012). "At 21 days after IRE treatment, the rats in the IRE group had similar percentages of CD3+ and CD4+ cells and a similar CD4+/CD8+ ratio compared with the non-tumor-bearing rats." (PMID 23139816, 2012). "We, therefore, tested if immunomodulation with SA-4-1BBL affects the conversion of conventional CD4+ T cells into CD4+CD25+FoxP3+ T cells in the tumor microenvironment and peripheral lymphoid tissues." (PMID 22870329, 2012). "In cancer-bearing animals or patients, Tregs expand, migrate to tumor sites, and suppress antitumor immune response mediated by NK cells, CD4+ and CD8+ T cells, and myeloid cells, through different molecular mechanisms." (PMID 22927872, 2012). "Several recent studies indicated that, in addition to acting as a helper for CD8+ T cells, CD4+ T cells are able to mediate direct killing of tumor cells in an MHC class II–dependent manner." (PMID 23071764, 2012). "Together, these data suggest a selective exclusion of CXCR3+ conventional T cells from the tumor-associated mucosa, with a concomitant recruitment of CCR4+ Treg and conventional CD4+ T cells." (PMID 22319577, 2012). "Results of these adoptive transfer experiments indicate that possible mechanisms for improved control of tumor growth in male recipients of female lymphocytes include both CD4 and CD8 T-cell recognition of antigens expressed by TRAMP-C2." (PMID 22493742, 2012). "It is very clear that progressive growth of intraocular tumors generates CD8+ Treg that inhibit CD4+ T cell dependent DTH responses to tumor Ags." (PMID 23060881, 2012). "Several studies on animal models have proved that the tumor immunosurveillance can be augmented when CD4+CD25+ Treg is inhibited or depleted." (PMID 22722448, 2012). "The use of an anti-PSMA x anti-CD3 bispecific diabody to selectively activate PSMA-specific CD8+ and CD4+ T cells and to recruit them to the tumor site revealed efficient inhibition of tumor growth in a xenograft model." (PMID 24213236, 2012). "It has been shown that CD4+ T cells can induce apoptosis in tumor cells through FAS- or TRAIL-dependent pathway." (PMID 22400040, 2012). "As both tumor size and CD3+ T infiltration are negative prognostic indicators, it is difficult to discern the influence of CD4+ FOXP3+ Treg on tumor progression." (PMID 23060881, 2012). "The frequencies of cells expressing α4β7 and the Th1 associated chemokine receptor CXCR3 were significantly decreased among CD4+ T cells in the tumor, while frequencies of CD4+CCR4+ lymphocytes were significantly increased." (PMID 22319577, 2012). "In this review we will focus on ways to provide optimal MHC class II-restricted tumor antigen presentation to CD4+ T helper cells as a crucial parameter to get optimal and protective adaptive immune response against tumor." (PMID 22849661, 2012). "Although CD8+ and CD4+ T cells are both required for tumor protection, the antibody depletion experiment indicates that CD8+ T cells play a more important role in controlling tumor growth." (PMID 23139820, 2012). "This highlights another crucial aspect of CD4+ T cells in tumor clearance and their preserved functionality upon infection strengthens H-1 PV value as a promising candidate in anticancer therapy." (PMID 22359669, 2012).